PF4 (platelet factor 4)
Diseases named in the same sentence as PF4 in open-access papers (continued):
Sharing a sentence is not in itself a finding about the gene and the disease.
bacterial infections (19 papers, 2016 to 2025). "On the basis of the conducted studies, RANTES protein, together with the platelet factor 4 (PF4), was classified in the group of chemokines, which play a key role in bacterial infections caused by intracellular pathogens." (PMID 30050949, 2018). "Based on these results, we suggest that the PF4-mediated protection against bacterial infection observed in our in vivo studies occurred primarily via the augmentation of phagocytosis and increased intracellular killing." (PMID 37868353, 2023). "Bacteria-bound PF4 has also been shown to expose neoantigens that elicited low titers of IgG antibodies 14 days after induction of bacterial infection that potentiated phagocytosis by human neutrophils, apparently through FcγR." (PMID 37868353, 2023). "It has been suggested that, in presence of bacterial infections, PF4 binds to polyanionic sequences on the surface of aerobic bacteria to form an antigenic complex that induces an early formation of antibodies against PF4/GAGs." (PMID 32846949, 2020). "Among the chemokines, IP-10, PF-4, and eotaxin were each reported as being expressed at significantly different levels in patients with bacterial versus non-bacterial infections." (PMID 27486746, 2016). "Systemic PF4 supplementation may be an efficient and controlled treatment of antibiotic-resistant bacterial infections." (PMID 37868353, 2023). "When platelets are activated by bacterial infection, surgical trauma and other stimulation factors, PF4 is released by activated platelets and may interact with HP or LMWHs to form PF4-HP or PF4-LMWH complex." (PMID 36090049, 2022). "Also, the inflammatory milieu in the setting of bacterial infections has been shown to enhance anti-PF4/heparin antibody formation and HIT." (PMID 28698883, 2017). "These neoepitopes cause production of anti-PF4/polyanion IgG antibodies that, in the case of bacterial infection, represent a mechanism by which platelets directly or indirectly promote bacterial phagocytosis, thus killing the opsonized anti-PF4/polyanion IgG bacteria." (PMID 34948438, 2021). "In the case of activation of platelets as a result of a bacterial infection, these cells, among others, affect the CXCL4 (PF-4) and CCL5 (RANTES) chemokine receptors on the surface of the vascular endothelium, induce "extravasation" of leukocytes." (PMID 34970260, 2021). "Anti-PF4 antibodies in atypical HIT-like syndromes could be triggered by presentation of various polyanions, eg, in settings of orthopedic surgery or bacterial infections." (PMID 40236285, 2025). "Building on our previous finding that treatment with P. aeruginosa strain PAO1 supplemented with Pf phage reduced pulmonary inflammation in response to bacterial infection, we examined P. aeruginosa infection in the absence of Pf4 phage." (PMID 37965262, 2023).
cardiovascular diseases (12 papers, 2012 to 2025). "PF4 has been implicated in cardiovascular disease and gastrointestinal conditions, and has the potential to promote oxidative and nitrosative stress, and subsequent inflammatory sequelae, although some studies argue otherwise." (PMID 39014464, 2024). "Similarly, PF4, a chemokine stored in platelet alpha granules and released upon activation, serves as a marker of ongoing platelet activation and is implicated in thrombo-inflammatory processes in cardiovascular diseases." (PMID 40806216, 2025). "In consideration of the in vivo platelet activation that could be induced by heparin, PF4 was not considered as a biomarker for cardiovascular disorder or thrombus formation." (PMID 28947991, 2017).
immune disorders (8 papers, 2007 to 2026). "The discovery of new PF4-related immune disorders underlying VTE during the pandemic has opened new avenues in thrombosis research, requiring further evaluations of new biological detection methods and clinical diagnostics approach to enhance patient care." (PMID 40123654, 2025). "We delve into the epidemiology, clinical features, and proposed mechanisms underlying thrombotic anti-PF4 immune disorders, with a particular focus on NETosis as a key mediator of these complications and its role in AAV pathology." (PMID 40276517, 2025). "The expanding spectrum of VITT-like disorders prompts further studies to better understand the mechanisms underlying thrombotic thrombocytopenic anti-PF4-triggered immune disorders." (PMID 40573981, 2025). "Future research should investigate NET inhibitors, such as PAD4 inhibitors, as a possible strategy to manage spontaneous anti-PF4 immune disorders and prevent severe thromboembolic complications." (PMID 40276517, 2025). "Three distinct etiologies of anti-PF4 immune disorders unrelated to heparin exposure have been characterized." (PMID 40276517, 2025). "We emphasize and investigate the pivotal role of NETosis in mediating the pathogenesis of thrombotic anti-PF4 immune disorders." (PMID 40276517, 2025). "More recently, there have been descriptions of anti-PF4-mediated immunothrombosis without prior heparin exposure, expanding the spectrum of thrombotic anti-PF4 immune disorders, beyond classic HIT." (PMID 40276517, 2025). "This case underscores the interplay between NETosis, ANCA vasculitis, and thrombotic anti-PF4 immune disorders, emphasizing the therapeutic potential of IVIG in mitigating NETosis-related complications." (PMID 40276517, 2025). "The role of procoagulant platelets was investigated in the diagnosis and understanding of heparin-induced thrombocytopenia (HIT), a prothrombotic immune disorder triggered by antibodies targeting platelet factor 4 (PF4)-heparin complexes." (PMID 41511295, 2025). "We review the epidemiology, pathogenesis, clinical manifestations, and management strategies of thrombotic anti-PF4 immune disorders, highlighting the roles of AAV and dysregulated NETosis as key triggers." (PMID 40276517, 2025). "Taken together, these studies provide further insight into molecular mechanisms of HIT and other immune disorders where anti-PF4 antibodies play a central role." (PMID 38467823, 2024). "HIT (heparin-induced thrombocytopenia) and HITT (heparin-induced thrombotic thrombocytopenia) are different manifestations of the same immune disease; during these conditions, the body releases IgG antibody (immune globulin G) against heparin-PF4 complex." (PMID 17996113, 2007). "In addition to platelet activation and endothelial injury mediated by PF4 antibodies, another mechanism contributing to thrombosis in thrombotic anti-PF4 immune disorders involves the activation of NETs." (PMID 40276517, 2025). "We have not discussed other PF4-immune diseases in this paper, but we recognize the emerging recognition these disorders have in the field and the future challenges these conditions will bring as we attempt to better identify and treat them." (PMID 39200826, 2024).
inflammation (8 papers, 2013 to 2026). Aberrant reaction of the microcirculation characterized by movement of fluid and leukocytes from the blood into extravascular tissues. "It is suggested that PF4 expression and PF4+ macrophages exert a diverse effect on cardiac inflammation in the RVes under intense light or hypoxia." (PMID 41281604, 2026). "It was reported that platelets accumulate and degranulate in the lungs in the models of airway inflammation, while the CD41+ microparticles and PF4/CXCL4 serve as markers of that degranulation." (PMID 23555611, 2013).
renal disease (8 papers, 2017 to 2023). "Currently, the mechanism of PF4 function in kidney disease remains poorly understood; thus, further research is needed to clarify this." (PMID 37834171, 2023). "Urinary vascular cell adhesion molecule-1 (VCAM1), platelet factor-4 (PF4), and the best-performing activated leukocyte CAM (ALCAM) were recently demonstrated as potential biomarkers of kidney disease activity in a cSLE cohort." (PMID 37893559, 2023).
vasculopathy (6 papers, 2017 to 2024). "PF4 is a marker for activation of endothelial cell and coagulation that was implicated in vasculopathy of SSc." (PMID 30245726, 2018). "Because of its roles in endothelial dissociation and angiogenesis, PF4 is potentially involved in vasculopathy of dengue syndromes." (PMID 28542641, 2017).
neurodegenerative disease (5 papers, 2013 to 2025). A disorder of the central nervous system characterized by gradual and progressive loss of neural tissue and neurologic function. "Similarly, KEGG analysis revealed up-regulation of neurodegenerative diseases, oxidative phosphorylation, and chemical carcinogenesis-reactive oxygen species pathways in Macrophages_Pf4 after PS-MPs treatment." (PMID 38167034, 2024). "PF4 and its variant form (PF4V1) are involved in numerous biological processes including inflammation and angiogenesis; two processes implicated in neurodegenerative disease such as ALS." (PMID 24224000, 2013). "Therefore, the aim of the proposal is to highlight the worth of PF4 in inflammaging of neurodegenerative diseases, which might provide a potential therapeutic strategy." (PMID 39364349, 2024).
hematologic malignancies (4 papers, 2013 to 2025). "As PF4 is secreted by platelets and hematologic malignancies always have reduced platelets." (PMID 23915341, 2013). "FINC, PF4, and CXCL7 levels were significantly decreased in patients with hematologic malignancies, while TIMP1 levels were elevated in those with chronic liver disease." (PMID 40864331, 2025). "PF4 and CTAP-III are platelet-derived chemokines, whereas there were always reduced platelets and WBC counts in hematologic malignancies." (PMID 25317080, 2014).
infectious disease (4 papers, 2018 to 2025). A disorder directly resulting from the presence and activity of a microbial, viral, or parasitic agent in humans. "The protective role of PF4 in infectious diseases is well-documented." (PMID 40864331, 2025). "Among several mediators released by platelets upon activation, sCD40L, PF4, PAF, and TXA2 have been previously involved in the formation of platelet–monocyte complexes in numerous infectious diseases." (PMID 29867977, 2018).
heart disease (3 papers, 2012 to 2026). "However, for the chemokine platelet factor 4 variant (PF-4var/CXCL4L1), released by platelets during thrombosis and with different properties as compared to PF-4/CXCL4, its role in heart disease is not yet studied." (PMID 22384011, 2012).
retinopathy (1 paper, 2014). "Borsey and colleagues showed that PF4 concentration was elevated in both DM with and without retinopathy compared to nDM controls." (PMID 24672719, 2014).
PF4 also shares sentences with these, for which no sentence is quoted: pulmonary embolism (7 papers); Disseminated intravascular coagulation (5); lung disease (5); ischemic stroke (4); vitiligo (4); acute coronary syndrome (3); mammary adenocarcinoma (3); myocarditis (3); pancreatitis (3); thrombophilia (3); acute lung injury (2); acute myocardial infarction (2); AIDS (2); allergic rhinitis (2); breast tumor (2); cardiac hypertrophy (2); colitis (2); gastric cancer (2); Insulin resistance (2); kidney injury (2); leptospirosis (2); migraine (2); multiple myeloma (2); neurological diseases (2); nonalcoholic steatohepatitis (2); pancreatic adenocarcinoma (2); peripheral arterial disease (2); Polycythemia Vera (2); renal cell carcinoma (2); viral diseases (2).
A further 104 diseases each share a sentence with PF4 in 2 papers or fewer.